SLITRK5 (SLIT and NTRK like family member 5)
Description:
Suppresses neurite outgrowth.
Synonyms: KIAA0918; LRRC11; bA364G4.2
Tractability: Antibody: its Gene Ontology location is reachable by antibodies, with high confidence; UniProt predicts a signal peptide or a membrane-spanning region. PROTAC: ubiquitination databases record sites on it; its protein half-life has been measured.
Gene: Protein-coding gene on chromosome 13 (87,671,371 to 87,696,272, forward strand). Ensembl gene ENSG00000165300.
Subcellular location: Membrane
Subcellular location (Human Protein Atlas): Vesicles
Pathways (Reactome):
Signal Transduction: RAC2 GTPase cycle; RAC3 GTPase cycle
Neuronal System: Receptor-type tyrosine-protein phosphatases
Gene Ontology:
Molecular function: protein binding
Biological process: synaptic membrane adhesion; axonogenesis; positive regulation of synapse assembly; regulation of trans-synaptic signaling by BDNF, modulating synaptic transmission
Cellular component: receptor complex; plasma membrane; membrane; postsynaptic density membrane
Genetic constraint (gnomAD): Loss-of-function variants: 23 observed, 58.79 expected, observed/expected ratio (o/e) 0.39, 90% interval 0.28 to 0.55. The upper end of that interval is the gene's LOEUF score, 0.55, which puts it in group 2 of 6, group 1 being the genes least tolerant of losing a copy. Missense variants: 1,289 observed, 1,304.3 expected, observed/expected ratio (o/e) 0.99, 90% interval 0.94 to 1.03. Synonymous variants: 637 observed, 569.36 expected, observed/expected ratio (o/e) 1.12, 90% interval 1.05 to 1.2.
Homologues: Orthologues: chimpanzee SLITRK5 (99% identical), macaque SLITRK5 (99% identical), dog SLITRK5 (98% identical), pig SLITRK5 (98% identical), mouse Slitrk5 (97% identical), rat Slitrk5 (97% identical), guinea pig SLITRK5 (89% identical), tropical clawed frog slitrk5 (72% identical), rabbit SLITRK5 (70% identical), zebrafish slitrk5a (64% identical), zebrafish slitrk5b (51% identical). Paralogues in human: SLITRK2 (46% identical), SLITRK3 (40% identical), SLITRK4 (39% identical), SLITRK6 (35% identical), SLITRK1 (29% identical), SLIT3 (17% identical), SLIT1 (16% identical), SLIT2 (16% identical), TLR9 (16% identical), GP5 (13% identical), LRRN2 (13% identical), LRRN1 (13% identical), and 13 more.
Diseases named in the same sentence as SLITRK5 in open-access papers:
SLITRK5 is named in the same sentence as 37 diseases in open-access papers, as found by Europe PMC text mining. Sharing a sentence is not in itself a finding about the gene and the disease. The quoted sentences say what the papers report.
obsessive-compulsive disorder (6 papers, 2017 to 2024). A disorder characterized by the presence of persistent and recurrent irrational thoughts (obsessions), resulting in marked anxiety and repetitive excessive behaviors (compulsions) as a way to try to decrease that anxiety. "Previously SLITRK5 deleterious mutations have been associated with Obsessive Compulsive Disorder." (PMID 35089926, 2022). "However, the treatment of fluoxetine, as a selective serotonin reuptake inhibitor (SSRI), which is mainly used for the treatment of depression and obsessive-compulsive disorder, can effectively alleviate reduce the excessive grooming behavior of SliTrk5 deficiency mice." (PMID 35872846, 2022). "Furthermore, there have been exhibiting complex interactions between SliTrk5 and many CNS disorders, including obsessive-compulsive disorder, attention deficit/hyperactivity disorder, autism spectrum disorders, and brain gliomas." (PMID 35872846, 2022). "A large number of studies have shown that SliTrk5 may be involved in the pathogenesis of CNS diseases, such as obsessive-compulsive-disorder (OCD), attention deficit/hyperactivity disorder (ADHD), glioma, autism spectrum disorders (ASDs), and Parkinson's disease (PD)." (PMID 35872846, 2022). "Currently, many investigations have indicated that SliTrk5 may be involved in the pathomechanism of many CNS diseases, including obsessive-compulsive-disorder (OCD), attention deficit/hyperactivity disorder (ADHD), glioma, autism spectrum disorders (ASDs), and Parkinson's disease (PD)." (PMID 35872846, 2022). "Summary of the behavioral alterations relevant to obsessive-compulsive disorder reported in the SAPAP3 KO mouse, Slitrk5 KO mouse, and EAAT3glo/CMKII mouse." (PMID 31803055, 2019).
autism spectrum disorder (3 papers, 2022 to 2024). A spectrum of developmental disorders that includes autism, and Asperger syndrome. "We further showed that gintonin successfully induced dendritic growth in striatal neurons, in which dendritic complexity was reduced by Slitrk5 and Shank3 knockdown, and could alleviate certain phenotypes related to obsessive–compulsive disorder and autism spectrum disorder." (PMID 36385759, 2022).
autism (2 papers, 2021 to 2022). Persistent deficits in social interaction and communication and interaction as well as a markedly restricted repertoire of activity and interest as well as repetitive patterns of behavior. "Thus, although no study has identified a specific role of SliTrk5 in the pathogenic mechanism of autism so far, SliTrk5 may be one of the genetic factors of autism from a genetic point of view." (PMID 35872846, 2022).
gastric cancer (2 papers, 2021 to 2022). A primary or metastatic malignant neoplasm involving the stomach. "In addition to playing an important role in the development of brain tumors, SliTrk5 is also involved in the process of tumorigenesis in other organs, such as colorectal cancer, thyroid tumors, gastric cancer, nasopharyngeal carcinoma, and lung squamous cell carcinoma." (PMID 35872846, 2022).
glioma (2 papers, 2022 to 2024). A benign or malignant brain and spinal cord tumor that arises from glial cells (astrocytes, oligodendrocytes, ependymal cells). "Especially in the gliomas, the expression of SliTrk5 was upregulated and associated with the pathological grading." (PMID 35872846, 2022). "A previous study has validated the expression of SliTrk5 is most widely expressed in different brain tumors, which was upregulated in gliomas and correlated with pathological grading." (PMID 35872846, 2022).
nasopharyngeal carcinoma (2 papers, 2021 to 2022). A carcinoma arising from the nasopharyngeal epithelium. "SLITRK5 involved radioresistance in nasopharyngeal carcinoma." (PMID 34504628, 2021).
behavioral disorders (1 paper, 2018). "Some candidates have been linked to intellectual disability (ID), such as CRBN, GPKOW, HERC1 and KCNA4, or to other behavioral disorders, such as CDC42EP4 and SLITRK5." (PMID 30102725, 2018).
brain tumors (1 paper, 2022). "In different types of human brain tumors, the expression of SliTrk5 was most widely in different human brain tumors, compared with other members of the SliTrks family." (PMID 35872846, 2022). "Recent years, SliTrk5 was reported to participate in the development of brain tumors." (PMID 35872846, 2022).
colorectal cancer (1 paper, 2022). A primary or metastatic malignant neoplasm that affects the colon or rectum. "SliTrk5 gene presented frequent genetic, epigenetic, and transcriptional alterations in colorectal neoplasia, which has been discovered by a study designed to compare and contrast the molecular profiles of laterally spreading tumors (LSTs) and colorectal cancer (CRC)." (PMID 35872846, 2022).
endometrioid carcinoma (1 paper, 2020). "In endometrioid carcinoma, PIK3CA and SLITRK5 mutations were detected frequently (40%)." (PMID 33207545, 2020).
epilepsy (1 paper, 2024). A brain disorder characterized by episodes of abnormally increased neuronal discharge resulting in transient episodes of sensory or motor neurological dysfunction, or psychic dysfunction. "Slitrk5 expression is associated with epilepsy; Slitrk5 expression was higher in the temporal neocortex of patients with temporal lobe epilepsy than that in non-epileptic individuals." (PMID 39334827, 2024). "Slitrk5 expression increased 24 h after status epilepticus in the temporal neocortex and hippocampus of rats with pilocarpine-induced epilepsy." (PMID 39334827, 2024).
leukemia (1 paper, 2016). A malignant (clonal) hematologic disorder, involving hematopoietic stem cells and characterized by the presence of primitive or atypical myeloid or lymphoid cells in the bone marrow and the blood. "With respect to their related mRNAs, SLITRK5 was shown to be expressed in leukemia, embryonic stem cells, subsets of endothelial cells, and neural tissues, and its dysfunction could impair corticostriatal circuitry and lead to obsessive-compulsive-like behaviors." (PMID 27599611, 2016).
medulloblastoma (1 paper, 2021). A malignant, invasive embryonal neoplasm arising from the cerebellum. "Given that Slitrk5 is also expressed in neural tissues, it is possible that Slitrk5 also modulates Hh signaling in neural cells and is therefore relevant to the oncogenesis of Hh pathway driven CNS tumors such as medulloblastoma." (PMID 34326333, 2021).
melanoma (1 paper, 2024). A malignant, usually aggressive tumor composed of atypical, neoplastic melanocytes. "The overexpression of SLITRK5 has been shown to enhance the growth, movement, and invasion of melanoma cells." (PMID 38933439, 2024). "Regulate SLITRK5 and Hedgehog signaling pathways to control the development of melanoma." (PMID 38933439, 2024). "In addition to inducing glioblastoma survival and migration through STA/AKT pathway, MUC21 also regulates SLITRK5 gene expression, thereby controlling Hedgehog signaling pathway to promote melanoma progression." (PMID 38933439, 2024). "This suggests that SLITRK5 may play a significant role in the development and progression of melanoma, a type of skin cancer." (PMID 38933439, 2024). "Additionally, by targeting SLITRK5 or modulating its activity, researchers may be able to develop new therapeutic strategies for treating melanoma and potentially other cancers that involve dysregulation of the Hedgehog signaling pathway." (PMID 38933439, 2024).
Parkinson disease (1 paper, 2022). A progressive degenerative disorder of the central nervous system characterized by loss of dopamine producing neurons in the substantia nigra and the presence of Lewy bodies in the substantia nigra and locus coeruleus. "The role of SliTrk5 in the neurodegenerative diseases, such as Parkinson's disease, has been starting to come out." (PMID 35872846, 2022). "Although no current researches have shown that there is a clear relationship between SliTrk5 and these neurodegenerative diseases, SliTrk5 may affect the function of midbrain dopaminergic neurons through above pathways, leading to neurodegenerative diseases such as Parkinson's disease." (PMID 35872846, 2022).
schizophrenia (1 paper, 2025). A major psychotic disorder characterized by abnormalities in the perception or expression of reality. "Slitrk5 (Odds ratio 6.69, P = 0.000917) and Fyn (Odds ratio 10.7, P = 0.000596) were molecules linked to an increased susceptibility to schizophrenia." (PMID 39774335, 2025).
thyroid tumor (1 paper, 2022). A benign or malignant neoplasm affecting the thyroid gland. "Moreover, in thyroid tissue, the expression of SliTrk5 was significantly downregulated in Trk-T1 transgenic thyroid tumor mice, which was revealed by a global genomic copy number analysis." (PMID 35872846, 2022).
Tourette’s disorder (1 paper, 2021). "Slitrk1 is a Tourette’s disorder candidate gene and Slitrk5 mouse mutants have obsessive compulsive-like behaviors." (PMID 34879283, 2021).
trichotillomania (1 paper, 2022). A disorder characterized by repetitive pulling out of one's hair resulting in noticeable hair loss; the individual experiences a rising subjective sense of tension before pulling out the hair and a sense of gratification or relief when pulling out the hair. "The exact cause of trichotillomania is still not clear, but three mouse models (Hoxb8 KO, Sapap3 KO, and Slitrk5 KO) with elevated grooming behaviors have been developed to study the pathophysiology of trichotillomania." (PMID 36066198, 2022).
central nervous system diseases (2 papers, 2022 to 2025). "Emerging research suggests potential associations between Slitrk5 and the pathogenesis of various central nervous system disorders, including OCD." (PMID 39851412, 2025). "Thus, this review has provided the foundation for subsequent integrated studies into the treatment of CNS disorders by figuring out the various functional roles of SliTrk5 in terms of the development of CNS." (PMID 35872846, 2022). "Therefore, it is necessary to understand the role of SliTrk5 in the development of the central nervous system and in the pathogenesis of central nervous system diseases." (PMID 35872846, 2022). "Additionally, studies indicate that manipulating Slitrk5 expression may facilitate the restoration of neural system function, making it a potential therapeutic target for central nervous system disorders." (PMID 39851412, 2025). "Increasing evidence has identified that SliTrk5 can modulate many important stages of central nervous system development, including axon and dendritic growth, neuron differentiation, and synaptogenesis, which may affect the pathological mechanism of many central nervous system diseases." (PMID 35872846, 2022).
neurodegenerative disease (2 papers, 2022 to 2024). A disorder of the central nervous system characterized by gradual and progressive loss of neural tissue and neurologic function. "The specific relationship and potential mechanism between SliTrk5 and neurodegenerative diseases will also be the focus and trend of future research." (PMID 35872846, 2022).
tumor (2 papers, 2007 to 2023). "Other genes, such as NOTCH3 and SLITRK5, have clear contributions to tumor development." (PMID 37214090, 2023).
SLITRK5 also shares sentences with these, for which no sentence is quoted: cancer (4 papers); Anxiety (2); attention deficit-hyperactivity disorder (2); alcohol dependence (1); amyloid (1); brain glioma (1); breast carcinoma (1); CNS tumors (1); head and neck cancer (1); Intellectual disability (1); lung carcinoma (1); lung squamous cell carcinoma (1); neurological diseases (1); psychiatric disorder (1); temporal lobe epilepsy (1).